CD4 (CD4 molecule)
Diseases named in the same sentence as CD4 in open-access papers (continued):
Sharing a sentence is not in itself a finding about the gene and the disease.
tumor (continued). "Circular DNA plasmids that encode tumor antigens are used as vaccines and are taken up robustly by antigen-presenting cells (APCs) to activate adaptive immunity through major histocompatibility complex (MHC) class I and II-restricted antigen presentation to CD8+ and CD4+ T cells." (PMID 37738978, 2023). "However, tumor cells expressing the KRASG12V-MITD construct, as evidenced by expression of a P2A-linked EGFP reporter, were similarly unable to stimulate TCR-engineered CD4+ T cells." (PMID 36512410, 2023). "In this study, we found that Her-2 positive patients tended to have lower differentiation and higher tumor grade, which may be related to the high expression of CD4+ T cells as well as the relatively low expression of CD8+ T cells in the tumor stroma of the Her-2 positive group." (PMID 38135990, 2023). "Moreover, a comparative study showed that DCs pulsed with tumor peptides released EVs that could induce a stronger anti-tumor CD4+ T-cell response than T-cells incubated with the peptides alone, which is evidence for the theory of enhanced immunity." (PMID 38203656, 2023). "In addition, another study found that atropine and muscarinic receptor 3 blockers reduced tumor weight, volume, and enhanced antitumor immune responses by increasing infiltration of CD4+ and CD8+ T cells and significantly reducing PD-L1 expression in a CRC mouse model." (PMID 38099288, 2023). "Of relevance, CD4+ T-cells may also be involved in this process, further stimulating anti-tumorigenic effector T-cell responses as well as activating NK(-T) cells to perform direct (tumor) cell killing." (PMID 37928528, 2023). "However, IFN-γ–producing CD4+ T cells can both indirectly and directly kill tumor cells." (PMID 38063199, 2023). "Furthermore, CD4(+) regulatory T cells (Tregs) play a crucial position in immune homeostasis and contribute to tumor progression in malignancies by suppressing effective tumor immunity." (PMID 37096492, 2023). "Tumor regression was associated with an enrichment of naive CD4, but not naive CD8 T cells." (PMID 37185301, 2023). "Our hypothesis is that CD4 T-cell activation is mediated by the release of tumor antigens by Lipo-MP-LPS-polarized M1 macrophages, which are known to have anti-tumor effects, and that their recruitment into the tumors is mediated by the chemokines produced in the tumor microenvironment." (PMID 37760603, 2023). "Peripheral CD4+CD25hiCD127low Tregs could be used for the evaluation of immunosuppressive status of patients with GI cancer and might assist in appraising the potential efficacy of tumor immunotherapies in GI cancer." (PMID 37210494, 2023). "Furthermore, human CD8 and CD4 cells could be detected in the tumor microenvironment by immunohistochemical staining." (PMID 36598909, 2023). "It has been observed that Th2 cytokines such as IL10 can directly suppress DC-mediated antigen presentation and T cell activation; these observations have led to the longstanding hypothesis that CD4+ T cell Th2 polarization is a mechanism of tumor immune escape." (PMID 37830618, 2023). "Notably, nigericin-induced pyroptosis could amplify the anti-tumor immune response by enhancing the infiltration and anti-tumor effect of CD4+ and CD8+ T cells." (PMID 37370831, 2023). "caf_C2_scissor may be closer to the antigen-presenting CAF phenotype, which are similar to antigen-presenting CAFs and can activate CD4+ T-cell in an antigen-specific manner confirming their immunomodulatory capacity, similar in function to the C2 subtype of Scissor_C2 tumor cells." (PMID 37091977, 2023). "Replication of other immune infiltration findings turned out to be more challenging—tumor purity and CD4+ lymphocytes infiltration were significantly higher in our and metacluster I samples, but was not in chordoma I from validation set, which may be due to insufficient number of observations." (PMID 37434245, 2023).
tumor (continued). "In summary, we suggest that the assessment of the immune system status (cytotoxic/effector features of T and NK cells and the expression of chemokine receptors on CD4+ T cells) along with the tumor burden might be a novel approach to predict response to treatment." (PMID 37174069, 2023). "In addition, the TME also plays essential role in regulating the function of TAMs and the cognate interaction between tumor-infiltrating CD4 + T-helper type 1 (Th1) cells and TAMs may shift the TAMs toward M1-like activity." (PMID 36864443, 2023). "To experimentally investigate how CD4+ T cell effector functions could be therapeutically directed against MHC-deficient tumours that evade CD8+ T cell immunity, we used enhanced green fluorescent protein (eGFP+) TRP-1 CD4+ TCRtg T cells and Venus+ Pmel-1 CD8+ TCRtg T cells for ACT immunotherapies." (PMID 37316667, 2023). "Therefore, targeting CD4+Treg in tumor therapy holds significant potential for development." (PMID 38250084, 2023). "Furthermore, our results strongly suggest that CIITA-induced MHC class II cell surface molecules in GL261-CIITA tumor cells are the key element in triggering the adaptive CD4+ Th cell anti-tumor response, most likely serving as antigen-presenting molecules for tumor-specific GBM peptide antigens." (PMID 36993983, 2023). "CX3CL1 expression was found to be positively connected with CD4+ T cells infiltration across most TCGA cancer types, as well as activated mast cells and M1 macrophage cells across several particular tumor types, indicating that CX3CL1 may also reflect the immune status in various cancers." (PMID 37153002, 2023). "Furthermore, MYL5 expression is markedly related to the tumor-infiltrating immune cells (TIICs), including cancer-associated fibroblast, B cell, CD8+ T cell, CD4+ T cell, macrophage, neutrophil, and dendritic cell, and related to immune molecules as well as the associated gene markers of TIICs." (PMID 36846347, 2023). "For example, resveratrol could enhance the anti-cancer immunity of tumor-bearing mice by promoting the accumulation of effector CD8+T cells and monocyte MDSCs and suppressing the number of tumor-derived CD4+CD25+Tregs and CD8+T cells suppressor granulocyte MDSCs." (PMID 37035188, 2023). "Additionally IFN-λ induces chemokines that recruit CD4+ T cells into the tumor microenvironment." (PMID 37374093, 2023). "Taken together, based on the results of our IHC analyses, decreased expression of STING in tumor cells might be involved in the low infiltration of both CD8+ and CD4+ T cells, and low expression of cGAS in tumor cells might be involved in the low infiltration of CD8+ T cells in pMMR/MSS CRC." (PMID 37345163, 2023). "Similarly, the CD4+ T cells showed reduced immune responses during tumor progression." (PMID 37143122, 2023). "Also, we observed that CD39 was more expressed in HC than in LC in the shared cluster of CD4+FOXP3+ T-cells (cluster #2) suggesting that CD39 could also be a marker of tumor-specific regulatory T-cells." (PMID 38057799, 2023). "CD4+ T cells subsets are plastic and can be converted to another lineage during tumor growth characterized by the opposite function, so an antitumor response depends on the cytokines presented in the tumor microenvironment and may be changed." (PMID 38067231, 2023). "Furthermore, tumor with low ferroptosis score may be infiltrated with more CD4+ T cells, CD8+ T cells, and less M1 macrophage." (PMID 35855531, 2023). "Therefore, propolis, which could increase the number of CD3+ and CD4+ TILs in the tumor microenvironment, can be classified as a natural product that is beneficial in preventing the CRC progression at the initial stage." (PMID 37960147, 2023). "Thus, our measurements at both transcriptional and protein levels suggest that certain tumor-infiltrating immune cells, particularly Tfh, resting CD4+ memory, and activated NK cells, could be key contributors to the outcomes of implanted xenografts." (PMID 37689699, 2023).
tumor (continued). "Moreover, the immune infiltrates in the colon polyps of Gpr15-KO mice as well as the human CRC tumor samples with reduced GPR15 expression showed significant increases in the population of pro-inflammatory immune cells such as IL-17+ CD4+ and IL-17+ CD8+ T cells." (PMID 38074634, 2023). "However, a paper published in 2021 demonstrated that a higher expression of AQP5 correlates with longer survival time (OS) and that high AQP5 expression is associated with a large number of infiltrating B lymphocytes and CD4+ lymphocytes, that is, TILs (tumor infiltrating lymphocytes)." (PMID 36766810, 2023). "Interestingly, these cells were better attracted to TGF-β-expressing tumor cells, inhibited the differentiation of human naïve CD4+ T cells into Treg cells, and could inhibit tumor growth in vivo in a xenograft model of HCC." (PMID 37371767, 2023). "Notably CD103+CD4+TRM are highly reduced in the tumor tissue compared with NCL." (PMID 37648263, 2023). "However, it has been shown that CD4+ T cells can also secrete some cytokines, such as IL-10, which can inhibit tumor angiogenesis through a variety of pathways, such as inhibiting endothelial cell proliferation and migration, and reducing the secretion of vascular endothelial growth factor." (PMID 37342362, 2023). "In addition, there were also studies demonstrating that radiotherapy may induce OX40 expression on tumor infiltrating CD4+ T lymphocytes." (PMID 37700338, 2023). "Among patients with HER2− BC, anti-tumor immune cells, such as CD8+ T cells and resting dendritic cells, were obviously downregulated in the high-risk group, while cancer-promoting cells, such as CD4+ T memory resting cells, were upregulated in the low-risk group." (PMID 37529698, 2023). "The activation of antigen-presenting cells and increased cytotoxic T lymphocyte infiltration into the tumor may be the mechanisms underlying the improved antitumor response, although it is still unknown if microbiota-regulated CD4+ T cells may also stop tumor progression." (PMID 37691931, 2023). "In UCEC, high expression of PHF6 decreased the infiltration of CD8+ T cells, CD4+ T cells, activated NK cells and M1 macrophages, which prevented tumour formation via immune surveillance, indicating that PHF6 might be a valuable marker for estimating the abundance of immune cells in UCEC." (PMID 36756714, 2023). "Furthermore, we sought to determine whether the observed tumor phenotype was contingent on the presence of CD4 or CD8 T cells." (PMID 37822487, 2023). "There is controversy over CD4 + T cells’ role in anti-cancer immunity, although most studies suggest that tumor-infiltrating CD4 + T cells may serve as a prognostic marker for Treg, a crucial mediator of tumor immunosuppression." (PMID 38017473, 2023). "To determine whether this mechanism may be preventing recognition of MHC-II+ tumor cells by CD4+ T cells, we cultured CD4+ T cells expressing our KRASG12V-specific TCR or the E6-specific F12 TCR with NCI-H2444 CIITA and HNSCC-56 CIITA, respectively, with or without anti–PD-L1–blocking Abs." (PMID 36512410, 2023). "In addition, antigen-specific CD4+ T cells have also been used to treat tumor patients." (PMID 37649123, 2023). "In this issue of the JCI, Taves, Otsuka, and colleagues show that murine tumor cell lines express the enzyme 11β-HSD1 and could reconvert inactive GCs to their active metabolites, which in turn promoted tumor growth by potentiating the immunosuppressive capacity of CD4+ Tregs." (PMID 37712416, 2023). "Additionally, the extracellular matrices of tumor-associated cells were disrupted in the absence of CD4 + T cells." (PMID 37907742, 2023). "cDC2s are crucial for the induction of CD4+ T helper cell 2 (Th2) responses, while cDCs1 have superior cross-presenting potential and induce cytotoxic T cells against virus-infected cells or tumor cells and are therefore explored as tools for anti-virus or anti-tumor vaccination strategies." (PMID 37251386, 2023).
tumor (continued). "In addition, by operating independently of direct tumor recognition, such as by marshaling a polyclonal CD8+ T cell response, ACT with CD4+ T cells may circumvent immune escape mechanisms associated with monoclonal CD8+ T cell ACT53,54." (PMID 37400675, 2023). "Our exploration revealing the positive correlation between occurrence of CSCs and Tregs encouraged us to further explore whether CSCs even though present in low numbers, can generate CD4+CD25+FOXP3+ immunosuppressive Treg cells from effector CD4+CD25− T lymphocytes during tumor initiation phase." (PMID 38038865, 2023). "This transition not only impedes the survival of T cells but also promotes the prevalence of CD4+ T cells over CD8+ T cells, corroborating the hypothesis that tumor matrices selectively impede the functionality of cytotoxic CD8+ cells while preserving CD4+ cells." (PMID 38332915, 2023). "Existing studies suggest that T cells CD4+ can target tumor cells in direct or indirect ways, either by eliminating tumor cells through the complex mechanisms, including the regulation of the tumor immune microenvironment, affecting antigen presentation, co-stimulation, and T cell homing." (PMID 37848933, 2023). "Thus, VAS score after treatment, changes of CD4+ T cell and tumor size were analyzed by Cox model." (PMID 37792639, 2023). "A combination treatment (i.e., RT + Ch/γ-PGA NPs) synergistically disrupted a 4T1 tumor improvement, which resulted in a considerable early tumor growth and splenic depletion, decreased the percentage of splenic immune-suppressive myeloid cells, and increased the anti-tumor CD4+IFN-γ+ population." (PMID 37238916, 2023). "Most notably, although only very few amounts of tumor-infiltrating immune cells were identified in tumor tissue, we discovered that “interface” cluster 9 exhibits significant immune and inflammation-related signatures with plenty of plasma B cell, follicular B cell, and Th2-like CD4 + T cells." (PMID 37164975, 2023). "In contrast, the presence of CD4+ TILs is associated with both positive and negative prognosis and tumor killing depending on tumor type, but overall may be beneficial to anti-tumor efficacy." (PMID 38143765, 2023). "Similarly, CD4+ T cell‐derived IFN‐γ mediates an increase in tumoricidal effectors, monocyte–macrophages, which secrete NO to induce remote inflammatory cell death in IFN‐unresponsive, MHC‐deficient tumor cells." (PMID 37829505, 2023). "Additionally, a subset of CD4+ T cells can directly participate in tumor cell elimination." (PMID 38328405, 2023). "Moreover, tumor regression mediated by cytotoxic CD4+ T cells is dependent on MHC‐II‐restricted manner, which could be enhanced by anti‐CTLA‐4 antibody." (PMID 37829505, 2023). "Clearly, weakening Treg cells and effectively activating or restoring effector CD4+ T cell responses are important for successful tumor clearance, and elucidating the mechanism of tumor regulation on CD4+ T cell differentiation might provide new targets for immunotherapy." (PMID 38062068, 2023). "Furthermore, a recent study revealed that immunizing with a combination of citrullinated enolase and vimentin peptides could stimulate strong CD4+ T-cell responses and potent anti-tumour effects, which may prevent tumour antigen escape." (PMID 37778382, 2023). "At 24 h after photoconversion ∼25% of CD8 T cells, CD4 T cells, regulatory T cells (Treg), and natural killer (NK) cells were Kaede Green+, and this proportion increased over time such that by 120 h, the majority of all TILs had entered the tumor since labeling." (PMID 35472220, 2022). "Notwithstanding they may indirectly contribute to anti-tumour immunity by inducing the reverse process, i.e., by converting Treg into anti-tumour effector CD4+ T cells, as recently suggested in patients with metastatic melanoma, gastrointestinal, and ovarian cancer." (PMID 35406451, 2022). "Also, Tumor-infiltrating PD1+CD4+ T lymphocytes were higher in patients with local recurrence." (PMID 35051220, 2022).
tumor (continued). "All of the infiltrating immune cells including CD4 + and CD8 + T cells, dendritic cells, neutrophils, B cells, and macrophages in the high-risk group were more abundant than those in the low-risk group as calculated using the Tumor Immune Estimation Resource (TIMER) algorithm." (PMID 36309694, 2022). "Notably, the SPHK1-MTA3 axis enhanced the tumor infiltration of CD4+CD25+FoxP3+ Tregs and F4/80+CD11b+CD206+MHC class II- M2-like tumor-associated macrophages, and this effect could be reversed by PD-1 mAb treatment." (PMID 36050478, 2022). "Moreover, agonistic engagement of SLAMF7 enhanced cytotoxicity of tumor-specific CD4+ T cells." (PMID 35237300, 2022). "T regulatory cells (Tregs) and T follicular helper cells (Tfh) derived from CD4+ T cells are closely related to immune homeostasis, which not only can maintain peripheral immune tolerance but also can inhibit T cell-mediated immune responses and promote tumor occurrence." (PMID 35935973, 2022). "For FTO, its expression level was positively correlated with CD8+ T cells, CD4+ T cells, macrophages and neutrophils, which suggested active anti-tumor microenvironment and might explain patients with higher transcription level of FTO possessed significant longer OS time." (PMID 35371987, 2022). "That high Eomes expression is increasingly observed in T cells at tumor sites and is positively correlated with increased survival in patients, suggests that its actions may go beyond promoting cytolytic activity in promoting CD4 T cell-mediated protection." (PMID 36358898, 2022). "Notably, CCL19 overexpression induced higher ratios of tumor-infiltrating conventional CD4+ T and NK cells but fewer Treg cells compared to CCL21, which may partially contribute to the more prominent anti-tumor effect of CCL19." (PMID 36654820, 2022). "The decrease of the CD4/CD8 ratio could contribute to tumor angiogenesis and immune evasion during the late FL stages, as we have previously demonstrated in DLBCL and in MZL, where a positive correlation between the decreased CD4/CD8 ratio and microvessel density was established." (PMID 35268349, 2022). "Secondly, EC subtypes with high tumor mutational burden (e.g., POLE-mutant/hypermutated and MSI-H) are highly immunogenic and exhibit more tumor-specific neoantigens, resulting in increased CD4 and CD8 tumor-infiltrating lymphocytes (TILs) and a compensatory upregulation of immune checkpoints." (PMID 36119020, 2022). "Moreover, the combination of ICIs and chemotherapy could synergistically induce antigen-specific immunity and enhance the infiltration of CD8+, and CD4+FoxP3 T cells to the tumor microenvironment." (PMID 35911702, 2022). "Moreover, with respect to MHC-I expression, tumor cells could also express MHC-II, which increases tumor recognition by the immune system and enhances CD4+ T cell immunity." (PMID 35008422, 2022). "Moreover, CD4+ T cells may control tumor growth through vessel normalization, the process which improves tumor vessel perfusion and oxygenation, enhances the efficacy of immunotherapy, and reduces metastasis." (PMID 36159781, 2022). "Here, we propose that the presence of N, CM CD4+ T cells and activated classical monocytes in the circulation, as well as a greater density of CD8+ T cells and CD20+ B cells and detection of TLSs in tumor tissue predispose and allow patients to benefit from immune interventions." (PMID 35671108, 2022). "Additionally, since previous literature has indicated that a significant proportion of CD4+ T-LGLL patients has an underlying disease or malignancy, it cannot be excluded that the triggering event is abnormal antigen stimulation such as tumor antigen." (PMID 35210405, 2022). "In addition, aside from a suppression of small tumor (1.0 mm ≤ Φ < 2.0 mm) numbers observed in Apc/Dok3/Cd4/Cd8 mice compared with Apc/Dok3 mice, tumorigenesis in Apc/Dok3 mice was not significantly affected by depletion of any of the tested lymphocyte populations." (PMID 36970719, 2022).